CENPBD2P (CENPB DNA-binding domains containing 2, pseudogene)
Synonyms: RPL23A_39_1676; RPL23AP79; formerly CENPBD1P1
Gene: Transcribed processed pseudogene on chromosome 19 (58,598,967 to 58,599,435, forward strand). Ensembl gene ENSG00000213753.
Diseases named in the same sentence as CENPBD2P in open-access papers:
CENPBD2P is named in the same sentence as 1 disease in open-access papers, as found by Europe PMC text mining. Sharing a sentence is not in itself a finding about the gene and the disease.
CENPBD2P shares sentences with these, for which no sentence is quoted: cancer (1 paper).